TSLP (thymic stromal lymphopoietin)
Diseases named in the same sentence as TSLP in open-access papers (continued):
Sharing a sentence is not in itself a finding about the gene and the disease.
asthma (continued). "The anti-TSLP monoclonal antibody, tezepelumab, has been shown to improve exacerbation rates, lung function, symptom control, and quality of life in patients with severe asthma." (PMID 38999286, 2024). "In addition, TAVO101 showed strong efficacy in both TSLP/OVA-induced asthma and imiquimod induced psoriasis models in hTSLP/hTSLPR double knock-in mice." (PMID 39726595, 2024). "Mast cells play a key role in asthma pathophysiology and airway remodelling through the release of a plethora of cytokines (e.g. TSLP, IL-33, IL-25, IL-4, IL-13 and TGF-β) and angiogenic factors (e.g. VEGF-A), as well as other inflammatory mediators and bronchoconstrictors." (PMID 38609094, 2024). "Thus, TSLP blockade with Tezepelumab represents an important advancement for severe asthma treatment." (PMID 38566968, 2024). "In a mouse asthma model, TSLP expression was elevated, and the NF-κB pathway was activated." (PMID 39334402, 2024). "Recent findings in clinical trials with anti-TSLP monoclonal antibody (tezepelumab) in uncontrolled severe asthma patients showed a significant reduction in asthma exacerbations and improved symptoms, an effect that was not confined to participants with eosinophilic airway inflammation." (PMID 38469627, 2024). "The application of upper airway TSLP and IL-25 measurement could therefore provide guidance on appropriate therapy in severe asthma; however, future studies are required to explore this possibility." (PMID 38999286, 2024). "Furthermore, tezepelumab, an anti-TSLP Ab, is applicable for the treatment of severe asthma and suppresses eosinophilic airway inflammation." (PMID 39624446, 2024). "The epithelial alarmin TSLP induces the expression of CUL5, which then interacts with and degrades OGT via K48-linked ubiquitination, inhibiting MAVS O-GlcNAcylation and IFN-β production, and eventually inducing asthma exacerbations." (PMID 38177117, 2024). "They play a key role in the development of allergic disorders such as asthma, allergic rhinitis, and atopic dermatitis because they are quickly activated by TSLP, IL-33, and IL25, and they release large quantities of traditional Th2 cytokines IL-4, IL-5, IL-9, and IL-13." (PMID 38931338, 2024). "The therapeutic potential of inhibiting TSLP in patients with asthma was also assessed by using Tezepelumab, which is a fully humanized monoclonal antibody (mAb) against TSLP that has been approved by the FDA for severe asthma treatment in the U.S. under the brand name of Tezspire in 2021." (PMID 38566968, 2024). "Alarmins such as IL-25, IL-33 and TSLP function at the initial stages of the allergy cascade and are anticipated to have a more comprehensive impact on airway inflammation, potentially offer more effective asthma management than currently therapies." (PMID 39717777, 2024). "While TSLP, IL-25, and IL-33 are acknowledged as the key promoters of the T2-skewed inflammatory response in asthmatic airways, there is increasing evidence for the role of additional epithelial-derived cytokines in asthma pathology." (PMID 39457624, 2024). "Notably, two of the identified genes are targets of known asthma drugs (i.e., TSLP [Tezepelumab] and IL4R [Dupilumab])." (PMID 39628479, 2024). "Although nasal epithelial TSLP may be effective at identifying patients with severe or steroid refractory asthma, it may be a poor biomarker in mild-to-moderate disease." (PMID 38999286, 2024). "Hence, instead of blocking downstream type 2 signature cytokines, the targeting of upstream alarmins, including IL-33 and TSLP has been proposed as an alternative treatment strategy for asthma and type 2 immunopathologies." (PMID 39497825, 2024). "There is a possibility that IL-4R or TSLPR is induced or increased in eosinophils from patients with severe asthma or atopic dermatitis, and these eosinophils may respond to IL-4, IL-13, or TSLP at concentrations up to 10 nM." (PMID 39624446, 2024).
asthma (continued). "Lastly, we were unable to include the latest addition to the biologics portfolio for asthma therapy, the anti-TSLP-antibody Tezepelumab, as it has only been approved by the European Medicines Agency in the fall of 2022, and thus 12 month data was not yet available at the time of study conclusion." (PMID 38515071, 2024). "This suggests that there is a dominant role for TSLP in corticosteroid-refractory severe asthma." (PMID 38469627, 2024). "Higher TSLP airway expression has been correlated with severity of asthma." (PMID 39267467, 2024). "In this review, we have identified studies focusing on TSLP in asthmatic airways in an effort to better understand the combined effect of TSLP and epithelial immunology in contributing to disease severity and propagating asthma pathogenesis." (PMID 38672419, 2024). "Tezepelumab also reduced AHR to mannitol, indicating that TSLP blockade might have additional benefits in asthma beyond reducing T2 airway inflammation." (PMID 38453256, 2024). "Epithelial cytokines, including TSLP, play a role in airway remodelling in asthma, and targeting them may help disrupt this process; thus, studies evaluating TZP’s impact on remodelling are valuable." (PMID 39552062, 2024). "This study revealed that OS inhibited Th2 differentiation by suppressing the TSLP and NF-κB pathways through the inhibition of NF-κB nuclear translocation, thereby reducing asthma-induced airway epithelial cell apoptosis and inflammation and alleviating asthma." (PMID 39334402, 2024). "Furthermore, UFPs increase the expression of IL-8, IL-33, and thymic stromal lymphopoietin (TSLP) in airway epithelial cells of patients with severe asthma." (PMID 38524119, 2024). "Similarly, the activation of TLR4 by cockroach allergens results in the release of TSLP, IL-25, and IL-33, further contributing to the inflammatory environment characteristic of asthma." (PMID 39457624, 2024). "This could be a novel mechanism that explains upregulated TSLP secretion in the asthmatic airways and consequent asthma exacerbations." (PMID 38469627, 2024). "In this review, we summarize the evidence of excessive TSLP production in airway epithelial cells in those with asthma, as well as how various important triggers have been shown stimulate TSLP production, leading to clinical consequences for asthmatic patients." (PMID 38672419, 2024). "In addition, TSLP activates effector cells in asthma such as human lung macrophages (HLMs), mast cells, and eosinophils." (PMID 38612858, 2024). "Admissions for asthma tended to be more frequent in children with TSLP detection (p = 0.07)." (PMID 36694181, 2023). "In addition to its fundamental role in the development of asthma, TSLP is known to play a significant role in the pathogenesis of several allergy diseases." (PMID 36601189, 2023). "Five monoclonal antibodies (mAb) targeting some molecules participating in type 2 (T2) inflammation (i.e., anti-IL4/13, anti-IL-5, anti-IL-5Rα, anti-IgE, anti-thymic stromal lymphopoietin (TSLP)) are now available for severe asthma and some of them are also indicated for CRSwNP." (PMID 37108417, 2023). "Elevated TSLP levels have been correlated with poor asthma control." (PMID 37685567, 2023). "Meanwhile, the release and production of TSLP may result in steroid resistance in moderate to severe asthma." (PMID 39282108, 2023). "Therefore, ILC2s under the influence of TSLP released from the airway epithelium are likely to play a crucial role in corticosteroid refractory type 2 airway inflammation that drives severe asthma." (PMID 37114915, 2023). "TSLP may also be considered a connection between the innate immune response to respiratory viral infections and the type-2 adaptive immune response in asthma." (PMID 37628907, 2023). "Therefore, TSLP signalling blockade is a highly promising therapeutic approach for allergic diseases and asthma." (PMID 37628907, 2023).
asthma (continued). "Tezepelumab is an antibody that blocks function of TSLP, and trials have demonstrated that patients with severe uncontrolled asthma have reduced exacerbations, better asthma control, and improved health-related quality of life after receiving Tezepelumab than patients on placebo." (PMID 37163370, 2023). "Moreover, several studies have shown enhanced TSLP gene expression in the asthmatic airway mucosa and increased TSLP levels in the BAL of patients with moderate-to-severe asthma." (PMID 37108740, 2023). "Tezepelumab is a fully human IgG2 mAb directed to the thymic stromal lymphopoietin —a cytokine of the alarmin family that, together with IL-25 and IL-33, is derived from epithelial cells and plays a very important role in the pathogenesis of asthma." (PMID 36836079, 2023). "In summary, our results show, for the first time, a substantial positive correlation between TSLP detected in nasal secretions of infants with severe bronchiolitis and the likelihood of needing asthma maintenance treatment and respiratory admissions up to the age of 4 years." (PMID 36694181, 2023). "TSLP and IL-33 are also potentially involved in the pathogenesis of asthma." (PMID 37569890, 2023). "Additionally, inhaled versions of IL4Rα and TSLP fragments are in early-stage clinical trials and potentially offer alternative asthma treatment to ICS." (PMID 37265457, 2023). "Moreover, TSLP is crucial in asthma-related inflammation in humans and mice, showing elevated levels in mouse models with antigen-related airway inflammatory disease; lung TSLP correlates with eosinophilia severity." (PMID 36834541, 2023). "Analysis of TSLP‐stimulated cell signatures in asthma should be undertaken in future studies." (PMID 35986608, 2023). "These factors make TSLP an attractive therapeutic target in asthma." (PMID 37334374, 2023). "Furthermore, teciprumab, a targeted drug corresponding to TSLP, is currently undergoing a phase 3 clinical trial in patients with poorly controlled asthma." (PMID 37809092, 2023). "Moreover, in paucigranulocytic asthma, TSLP mediates multifaceted cross talks between inflammatory cells, such as mast cells and airway structural cells, such as epithelial cells, smooth muscle cells and fibroblasts." (PMID 37628907, 2023). "TNFα, lung fibroblasts, and TSLP form an important axis to promote type 2 immune responses in asthmatic lungs that may contribute to the chronic inflammation in asthma." (PMID 36760534, 2023). "A human monoclonal antibody specific for TSLP, known as tezepelumab (Tezspire), was approved by the US Food and Drug Administration in 2021 as an add‐on maintenance treatment for patients aged ≥12 years with severe, uncontrolled asthma." (PMID 37165746, 2023). "In conclusion, through the NF-κB and MAPK pathways and histone modification, LTRAs increased IL25, IL33, and TSLP mRNA expression in lung and bronchial epithelial cells, which might provide support for the decreased effectiveness of LTRAs in asthma therapy." (PMID 36674744, 2023). "Skin-derived TSLP may in fact be sufficient to support the atopic march from skin sensitization to asthma; yet, since TSLP also has homeostatic roles, co-factors in the surrounding microenvironment are likely important." (PMID 36830738, 2023). "TSLP is also released in response to epithelial stimuli (e.g., allergens, viruses, bacteria, pollutants, and smoke) and initiates multiple downstream innate and adaptive pathways involved in asthma." (PMID 36902079, 2023). "Inhibition of TSLP represents a novel approach to treat the diverse endotypes of asthma." (PMID 36902079, 2023). "This may provide a mechanism linking TSLP directly to corticosteroid resistance in ILC2s responses and corticosteroid refractory asthma." (PMID 37114915, 2023). "It has been also proposed that several T2 cytokines such as TSLP or periostin could be used as prognosis biomarkers for the development of asthma." (PMID 36694181, 2023).
asthma (continued). "From biopsy sections of mild atopic patients with asthma, it has been seen that allergen challenge induced an increase in IL-25, IL-33, and TSLP levels in the bronchial epithelium and submucosa, with a positive correlation between these cytokines and the extent of airway obstruction." (PMID 36830972, 2023). "ILC2s produce a large amount of IL-5 and IL-13 in response to epithelial-cell-derived cytokines, such as IL-25, IL-33, and thymic stromal lymphopoietin (TSLP), which are considered to play an essential role in the pathogenesis of allergic disorders, including asthma." (PMID 37371472, 2023). "The expression of TSLP has been observed to be higher in asthma patients." (PMID 36601189, 2023). "According to our results, the association between TSLP and asthma development seems to be independent of the atopic status." (PMID 36694181, 2023). "In T2-high asthma, the interaction of the airway epithelium with the external exposome activates the release of specific mediators—epithelial-derived alarmins—as thymic stromal lymphopoietin (TSLP), IL-25, and IL-33, leading to the production of IL-4, IL-5, and IL-13." (PMID 37761964, 2023). "Moreover, a second candidate, ABY-062, is about to be proposed for clinical studies as an inhalable agent that targets the cytokine thymic stromal lymphopoietin (TSLP) for treating asthma." (PMID 37240041, 2023). "The Global Initiative for Asthma (GINA) recommends the corticosteroid, azithromycin, anti-IL4R, anti-thymic stromal lymphopoietin, long-acting muscarine anticholinergic, short-acting β-agonists, and anti-IgE antibody omalizumab for the treatment of severe asthma." (PMID 37245015, 2023). "Consequently, airway epithelium in patients with T2 asthma overproduces a broad pallet of pro-inflammatory cytokines and mediators including alarmins (IL-25, IL-33, TSLP), as well as IL-6, IL-8, IL-1α/β, RANTES, or TNF in response to environmental triggers." (PMID 37199256, 2023). "Furthermore, Fos can be induced by Thymic stromal lymphopoietin and inhibited by Dexamethasone in the peripheral blood mononuclear cell of the patients with severe asthma." (PMID 36726128, 2023). "Thymic stromal lymphopoietin (TSLP) is a pleiotropic cytokine that is involved in the pathogenesis of inflammatory diseases and asthma, but the expression and biological implications of the existence of two isoforms, long TSLP (lTSLP) and short TSLP (sTSLP), in RA have yet to be elucidated." (PMID 36726974, 2022). "Addressing this gap is critical as anti-TSLP and other biologics targeting type 2 inflammation represent a promising future alternative to reduce morbidity and mortality in children with severe uncontrolled asthma." (PMID 36245744, 2022). "Similarly, the number of ILC2s in nasal biopsies was shown to positively correlate with TSLP levels in nasal tissues of patients with severe asthma and chronic rhinosinusitis." (PMID 35572064, 2022). "In asthma, the results of clinical trials of anti-TSLP therapy are very convincing." (PMID 35572064, 2022). "This led to the concept of targeting TSLP in human asthma at the level of the airway epithelium." (PMID 36311787, 2022). "Collectively these novel molecular and clinical data indicate that TSLP may play a role in the pathogenesis of pediatric asthma, including lower airway inflammatory and obstructive features characteristic of the disease." (PMID 36245744, 2022). "In our current study we found that children with severe asthma have higher TSLP levels." (PMID 36245744, 2022). "In the present study, we found that TSLP could induce marked ROS production, which is an important factor in the pathophysiology of asthma." (PMID 35292112, 2022). "Comprehensive studies in mice have elucidated the role of mouse TSLP (similar to human lfTSLP) in the development of asthma and other type 2 inflammatory manifestations, represented by the induction of downstream responses by TSLPR-expressing cells such as DCs, ILC2s, basophils and mast cells." (PMID 36311787, 2022).
asthma (continued). "While prospects are promising for prevention of TSLP-mediated inflammation through tezepelumab, therapies against the other two alarmins, IL-25 and IL-33 are currently lagging as effective treatments in asthma." (PMID 36311787, 2022). "Results from the NAVIGATOR trial using tezepelumab suggest that targeting TSLP in patients with severe, uncontrolled asthma may prevent exacerbations as well as improve lung function based on improved prebronchodilator FEV1 values." (PMID 36311787, 2022). "The overarching goal of this study was to test the hypothesis that pulmonary TSLP levels in children with asthma correlate with clinical severity, companion airway inflammation and lower airway obstruction." (PMID 36245744, 2022). "In terms of an innate immunological barrier, epithelial cell activation and the release of epithelial cell cytokines, such as the alarmins, IL-25, IL-33, and thymic stromal lymphopoietin (TSLP), play a significant role in causing and exacerbating allergic diseases such as asthma." (PMID 36077310, 2022). "In addition, Tezepelumab, which blocks TSLP, an important regulator of airway remodeling, significantly reduced exacerbations, and improved lung function in patients with uncontrolled asthma." (PMID 35408882, 2022). "Besides, we found a positive correlation between BIRC3 and IL-10, IL-33, and TSLP in induced sputum of asthma (p < 0.05)." (PMID 35287655, 2022). "Tezepelumab is an anti-TSLP human monoclonal antibody that normalizes type 2 cytokine levels and in clinical studies significantly reduced exacerbation rates vs placebo in patients with severe, uncontrolled asthma." (PMID 36685501, 2022). "In some asthma models, TSLP-driven allergic inflammation is mediated by ILCs." (PMID 35406669, 2022). "Moreover, TSLP expression has been shown to correlate with airway obstruction and disease severity in asthma patients." (PMID 35572064, 2022). "We found the severe asthma cohort had overall increased levels of TSLP (median values, pg/mL, 0.409 vs. 0.923, p = 0.016) and IL-5 (median values, pg/mL, 0.248 vs. 0.940, p = 0.016) compared to the mild/moderate asthma group." (PMID 36245744, 2022). "Interestingly, this includes rs1837253, which regulates TSLP production in nasal epithelial cells and is significantly positively correlated with the manifestation of asthma in CRS patients." (PMID 35572064, 2022). "Studies indicate that IL-25, like IL-33 and TSLP, has a prime position in promoting T2 asthma." (PMID 36311787, 2022). "Furthermore, the importance of TSLP and IL-33 in the pathogenesis of asthma has been confirmed by studies showing efficacy of drugs that block these cytokines." (PMID 35406669, 2022). "TSLP, IL-33 and IL-25 are epithelial cell-derived cytokines that stimulate group 2 innate lymphoid cells (ILC2s) to release type 2 cytokines such as IL-5 and IL-13 and play an important role in asthma pathogenesis." (PMID 35292112, 2022). "In contrast, the concentration of TSLP in the induced sputum of asthma patients during virus-induced exacerbations was inversely related to the number of eosinophils, suggesting different mechanisms of action of TSLP in acute exacerbations compared with chronic eosinophilic inflammation." (PMID 35572064, 2022). "TSLP, IL-25 and IL-33, are designated as alarmin cytokines because their release from microbial, pollutant or allergen-perturbed epithelia heralds the onset of inflammatory responses in asthma." (PMID 36311787, 2022). "In T2-low asthma, respiratory viruses, bacteria, fungi and cigarette smoke can induce the release of epithelium-derived alarmin [i.e., IL-33, thymic stromal lymphopoietin (TSLP) and IL-25], which activate a variety of cells of the innate and adaptive immune system." (PMID 34342773, 2022).